LEP (leptin)
Diseases named in the same sentence as LEP in open-access papers (continued):
Sharing a sentence is not in itself a finding about the gene and the disease.
Obesity (continued). "In addition, even in the presence of hyperleptinemia, insulin resistance, a hallmark of diabetes mellitus (DM), may also contribute in loss of leptin sensitivity particularly in certain conditions like obesity that may lead to leptin resistance." (PMID 31929574, 2020). "The authors concluded that “leptin can initiate degenerative processes and within the inflammatory environment seen in degenerate discs, it can potentiate degenerative process, thus supporting a biochemical link in the relationship between intervertebral disc degeneration, back pain, and obesity.”." (PMID 33396484, 2020). "In the link between obesity and increased permeability, leptin could play a pivotal role." (PMID 32295104, 2020). "Leptin treatment leads to reduction in food intake and thus in body mass in ob/ob mice, demonstrating that it was indeed the lack of leptin that caused obesity in the ob/ob mice." (PMID 31774114, 2020). "Straightforward research aiming to characterize the direct impact of in situ leptin on triggering eosinophil recruitment and activation are still missing, despite the fact that some reports indicate that leptin may regulate eosinophils in low- versus high-fat diets mouse models of obesity." (PMID 33117286, 2020). "The blunting effect of obesity on GW9662 and αPD-L1 could be due to obesity-triggered elevation of adipocyte-derived factors such as PD-L1, leptin, and IL-8, all of which are known to antagonize host antitumor immunity and the therapeutic efficacy of checkpoint blockade immunotherapies 11, 28-30." (PMID 32226299, 2020). "Therefore, we measured circulating leptin levels in animals exposed to maternal obesity." (PMID 32163401, 2020). "Moreover, the effect of increased weight loading on body weight seems to be robust when comparing with the variable, often small, effects described in randomized controlled trials of exercise and other life style changes as well as of leptin treatment on body weight in most cases of obesity." (PMID 32510046, 2020). "In this study, excessive leptin expression was also found in the mice with obesity and excessive mechanical force induced TMJOA-like changes, especially in HFD mice, suggesting that this proinflammatory effect of leptin may also promote the development of TMJOA." (PMID 33060739, 2020). "Although the authors were not able to demonstrate which gene instigated obesity, these animals represent a very interesting model to identify the mechanisms underlying obesity-related insulin resistance and impaired glucose tolerance in the absence of aberrant leptin signaling or HDF-feeding." (PMID 35330637, 2020). "Additionally, the level of serum leptin was higher in the obese population than in non-obese men, and elevated serum leptin was responsible for the obesity-associated increase in diastolic blood pressure." (PMID 33114326, 2020). "This review of the current literature suggests “back-to-basics approach”—we should first try to establish the nature of leptin signaling pathway in obesity, with focus on the intervertebral disc and its residents, before we try to repair something that maybe not broken at all." (PMID 33396484, 2020). "However, in most cases of obesity, the endogenous serum leptin levels are high, and there is limited effect by leptin treatment when evaluated in animal studies or randomized clinical trials, indicating that other homeostatic mechanisms also might contribute." (PMID 32510046, 2020). "In addition, we examined whether leptin-induced responses were altered by dietary status and obesity (i.e., comparison of Ca+2 signaling in the DVC of lean rats maintained on a standard chow or obese rats maintained on a 60% high-fat diet)." (PMID 32152264, 2020). "Moreover, in obesity models (diet-induced-obesity and ob/ob mice), intraperitoneal injection of leptin increases BAT UCP1 mRNA levels and activity without causing significant changes in mice locomotor activity." (PMID 32069871, 2020).
Obesity (continued). "Acute decreases in leptin concentrations in response to acute bouts of aerobic and resistance exercise have been described but, in the presence of an altered hypothalamic set point in obesity, theoretically lead to compensatory overeating and decreased metabolic rate, impairing weight loss." (PMID 32604889, 2020). "Similarly, relapsing-remitting MS patients also displayed an inverse correlation between frequency of Tregs and serum leptin levels, indicating that leptin may act as a link between obesity, Treg numbers and immunological tolerance." (PMID 32153577, 2020). "Taken all together, since hypothalamic inflammation results in central leptin resistance and hepatic insulin resistance, blocking the peripheral and central inflammation induced by a high fat diet could have the potential to treat obesity and GDM." (PMID 32630697, 2020). "Moreover, sleep deprivation may result in metabolic disorders like abnormal leptin levels, which can also lead to obesity." (PMID 32192114, 2020). "Obesity exerts a significant metabolic effect and is considered to be a state of chronic, low-grade inflammation leading to systemic consequences related to the disturbed secretion of hormones and cytokines including leptin, adiponectin, and chemokines that regulate inflammation." (PMID 33008429, 2020). "Therefore, in parallel, LepR in non-hypophysiotropic neurons may be up-regulated to contribute to obesity-induced sympathoexcitation, which is dependent in part on increased leptin levels." (PMID 32538782, 2020). "Importantly, our results identify mast cells as modulators of leptin-driven eosinophilic reaction are in line with recent postulations that adipose tissue resident mast cells or the obesity-related increased mast cell population are modulators of adipose tissue homeostasis and inflammation." (PMID 33117286, 2020). "Elevated levels of leptin in obesity might contribute to the release of pro-inflammatory cytokines." (PMID 32547431, 2020). "As such, increasing leptin signaling may be a target for interventions aiming to increase adiponectin expression, enhance insulin sensitivity, and improve the cardiometabolic profile in obesity." (PMID 32131811, 2020). "On the other hand, obesity is also associated with increased morbidity and mortality in response to select infections such as bacterial cellulitis, influenza, and coronavirus, although the role for leptin in this setting has not been determined." (PMID 33584724, 2020). "Interestingly, it has been proposed that, in part by increased intra-follicular levels of leptin, obesity directly affects ovarian functions in PCOS and may induce a relative resistance to gonadotropins." (PMID 32927680, 2020). "However this phenomenon is well described and may be due to ‘leptin resistance’, whereby individuals with obesity demonstrate paradoxically high levels of circulating leptin but diminished leptin sensitivity." (PMID 33004989, 2020). "In addition, in another study, also it has reported that GTE could improve MSG-induced obesity and reduce insulin and leptin concentrations." (PMID 32489556, 2020). "Additionally, leptin was elevated among women who drink more soda, suggesting that leptin resistance may be common among patients with obesity." (PMID 32977648, 2020). "Therefore, monitoring adiponectin and leptin in combination with the measurement of obesity may provide a simple, easy, and cost-effective approach for early detection of MetS." (PMID 32397260, 2020). "Interestingly, our finding that AgRP neurons become resistant to both ghrelin and CCK, along with substantial prior evidence of leptin resistance in obesity, suggests that AgRP neurons may become generally resistant to hormonal input following weight gain." (PMID 32720646, 2020). "Leptin resistance is a relevant factor in the pathogenesis of obesity, and epigenetic modifications could contribute to leptin expression and signaling disturbances in obesity." (PMID 33532487, 2020).
Obesity (continued). "Systemic low-grade inflammation may be a contributing factor for the lower levels of Tregs in obesity, however, it is interesting to note that leptin has been shown to induce proinflammatory cytokines and inhibit Tregs in leptin/leptin receptor – sufficient mice fed high-fat diet." (PMID 31191312, 2019). "Leptin, a product of the ob gene which is primarily produced by adipose tissues, helps to regulate the hypothalamic-pituitary-gonadal axis and plays a vital role in obesity, hyperinsulinemia, and increased insulin resistance in the polycystic ovary syndrome (PCOS) patients." (PMID 32025443, 2019). "Although starvation and obesity could not, on the surface, be more different, starvation is actually a key physiologic feature of both insulin and leptin deficiencies." (PMID 30357355, 2019). "Therefore, leptin can be an important contributor to obesity-induced kidney injury." (PMID 31480394, 2019). "Hence, obesity-associated increases in CCL2 and CCL5 levels, together with an increase in estrogen and pro-inflammatory mediators such as leptin, IL-6, IL-1β, and TNF-α could facilitate MDSC accumulation." (PMID 31475003, 2019). "Therefore, obesity with increased levels of adipokines, like leptin and vaspin, might inhibit or delay cell apoptosis, which was accordance with our present results." (PMID 31772700, 2019). "The ability of BAPN to reduce leptin levels in vivo and prevent the leptin-mediated induction of profibrotic mediators and ROS in cardiac cells suggests that the interaction between leptin and LOX regulates downstream signaling pathways underlying the development of myocardial fibrosis in obesity." (PMID 31766500, 2019). "Therefore, hyperleptinemia in obesity may arise as a compensatory mechanism to overcome leptin resistance." (PMID 31694146, 2019). "In conclusion, a set of miRNAs present in breast milk, in close conjunction with leptin and adiponectin, are natural bioactive compounds with the potential to modulate infant growth and brain development, an interplay that is disturbed in the case of maternal overweight/obesity." (PMID 31661820, 2019). "RBP4 is thought be related to obesity, insulin resistance, type-2 diabetes, and metabolic syndrome and is suggested to be an early indicator of the development of insulin resistance and metabolic syndrome, and that this adiponectin is more sensitive to insulin than leptin, IL-6, and CRP." (PMID 30761880, 2019). "Short-term administration of leptin into the cerebral ventricles increases renal sympathetic activity, while long-term intravenous leptin infusions in nonobese rodents at rates similar to the levels found in severe obesity increase arterial pressure and heart rate through adrenergic activation." (PMID 31500090, 2019). "Moreover, a central resistance to leptin has also been described during obesity, which may expose subjects to the same manifestations as the lack of leptin, that is, cognitive impairments (if confirmed)." (PMID 30893833, 2019). "Hence, our results are in line with other reports whereby obesity might decrease LEP promoter activity by decreasing the affinity of some transcription factors for their cognate binding sites." (PMID 30732639, 2019). "Thus, CNS leptin protects from ectopic lipid accumulation via a brain-vagus-liver axis and may be a therapeutic strategy to ameliorate obesity-related steatosis." (PMID 31222048, 2019). "We surmise that obesity and hyperinsulinemia induced by leptin deficiency, rather than the activation of hepatic stellate cells by leptin, might make a greater contribution to steatohepatitis and subsequent fibrosis progression in ob/ob mice fed FFD." (PMID 31023717, 2019). "Therefore, stimulation of brain leptin signaling, could be a strategy to ameliorate the hepatic steatosis not only in lipodystrophy but also in conditions such as obesity and diabetes." (PMID 31222048, 2019).
Obesity (continued). "On the other hand, Akt inhibition resulted in reduced vascular leptin response in both groups, but this effect was less pronounced in Ob rats compared to C rats, suggesting that leptin promoted vascular relaxation partially mediated by Akt activation in obesity." (PMID 30949067, 2019). "Therefore, promoter methylation was investigated at these loci, as well as at previously identified gene promoters reported in the literature to be regulated by DNA methylation in response to high-fat diet, obesity or T2D (Leptin, Pparg, Glut4, Fasn, Irs1, Hmox1, Fabp4)." (PMID 30728429, 2019). "Leptin, which is considered as a key molecule in the pathophysiology of obesity, could play an important role in sarcopenic obesity, since leptin resistance was observed in subjects with sarcopenic obesity in comparison with subjects having either obesity or sarcopenia." (PMID 32009986, 2019). "Only on the basis of obesity, AP may promote leptin releasing from adipose tissue." (PMID 30635594, 2019). "If supported by longitudinal data, these findings could contribute to our understanding of risk for obesity in youth, possibly identifying youth with LOC eating and greater trait anxiety as a high-risk group for weight gain potentially through dysregulated leptin." (PMID 31547319, 2019). "Rare and pathogenic variations in the MC4R (MIM:155541), POMC (MIM:176830), LEP (MIM:164160), LEPR (MIM:601007) and few other genes of LEP‐melanocortin pathway have been found and very less frequency of mutations was accounted in different studies due to complexity in the pathogenesis of obesity." (PMID 31070016, 2019). "Regarding the positive relationship between leptin and adiponectin in the present study, recently, it was demonstrated that leptin upregulates adiponectin expression; and, that the decreased adiponectin expression in established obesity may be secondary to impairment of leptin signalling." (PMID 31312222, 2019). "Therefore, abundant secretion of leptin in obesity could affect miR-26b to limit the preadipocyte differentiation process through PTEN, and PPARγ and C/EBPα, however, the detailed mechanism remains to be fully elucidated and clarified." (PMID 31408957, 2019). "The data regarding miRNA-dependent direct regulation of leptin in cell, animal, and human models of metabolic disorders appear to be highly limited, which may be due to the fact that animal models of obesity and diabetes frequently involve gene knockouts of leptin or leptin receptors." (PMID 31408957, 2019). "Research on the mechanism of acupuncture in treating simple obesity is still indefinite, while some possible functions of acupuncture have been partly elucidated: remodel white adipose tissue, regulate central nervous system and metabolic factor, and improve insulin resistance and leptin resistance." (PMID 31651840, 2019). "We administered PPB to diet-induced obesity (DIO) and leptin-deficient (ob/ob) mice, evaluated macrophage activation, polarization, and changes of inflammatory cytokine level in adipose tissue and brain, and determined the effect of PPB on leptin resistance or leptin sensitivity in the brain." (PMID 31739649, 2019). "This may be as a result of the link between obesity and leptin." (PMID 31333585, 2019). "Regardless, the chronicity of obesity may suggest that any leptin regulation of adipocyte autopahgic process as we show here, even if with a small effect size due to LepR expression and/or to obesity-related leptin resistance, may nevertheless bear physiological relevance over time." (PMID 30676227, 2019). "Leptin can inhibit eating, and its reduction may be involved in excessive eating and obesity." (PMID 31509542, 2019). "As leptin is a major regulator of B cell development, maturation, and activity, alterations to the adipokine balance due to obesity may directly affect B cell function, B cell interactions with other lymphoid cell types such as T-follicular helper cells, and antibody class-switching." (PMID 31134099, 2019).
Obesity (continued). "How obesity can influence the development and prognosis of human breast cancer remains unknown, although several factors secreted by adipocytes including aromatase, leptin, adiponectin, oestrogens, and insulin-like growth factor-1 have been implicated." (PMID 31091785, 2019). "However, obesity provokes a Th1 response, initiated by hypertrophic adipocytes secreting inflammatory adipokines like leptin, resistin, and angiotensin II as well as generating so-called damage-associated molecular patterns (DAMPs) by necrotic cell death and lipids associated with lipotoxicity." (PMID 31349725, 2019). "Leptin may act as a molecular link between obesity and breast cancer." (PMID 30823902, 2019). "In addition, leptin together with resistin could also function as a pro-inflammatory molecule in the presence of obesity, while adiponectin and ghrelin have anti-inflammatory properties." (PMID 30715588, 2019). "Furthermore, increased inflammatory responses in the hypothalamus may produce leptin resistance, leading to defective food intake in dietary fat-induced obesity." (PMID 31731503, 2019). "Strengths of this study include its study design which raises interesting questions regarding the interplay of leptin, insulin and C-peptide during the neonatal period and how it would influence the programming of obesity during infancy, childhood and may be adulthood." (PMID 31975995, 2019). "Leptin may contribute to the recovery of muscle and bone enhanced by obesity in mice." (PMID 31648235, 2019). "Furthermore, DNAm of LEP was associated with this trajectory at one CpG site and early persistent obesity at another, though mediation analysis was not significant." (PMID 31464656, 2019). "One possibility is that a combination of high cortisol, potentially due to higher trait anxiety, and elevated leptin may drive youth with LOC eating to engage in “stress eating,” and thus increase the risk for excess weight gain and the development of adverse obesity-related health markers." (PMID 31547319, 2019). "Moreover, the increase in bone mineral density observed in obese humans might be secondary to leptin resistance, critical in human obesity development." (PMID 31500090, 2019). "In conclusion, obesity may result in the decreased intestinal leptin/ObR-b binding, lower bacterial richness, distinct phylogenetic clusters of ileal bacterial communities, increased intestinal inflammatory injury and the insufficient IEC proliferation during AP attack." (PMID 30635594, 2019). "have drawn attention to the likely existence of leptin-independent signals of the obese state that might serve to restrain the indefinite progression of a state of positive energy balance and ever increasing obesity." (PMID 30639358, 2019). "Therefore, the adiponectin to leptin ratio is decreased in obesity-related adipose tissue." (PMID 31500658, 2019). "Similarly to leptin, insulin resistance may occur in obesity as a consequence of complex mechanisms." (PMID 31467596, 2019). "Despite the evolutionary perspective that leptin’s physiology evolved to limit its ability to act as a potent antiobesity hormone, studies in rodents and humans have provided evidence that forced overfeeding can indeed engage physiologic pathways that resist obesity." (PMID 30357355, 2019). "In contrast, although the discovery of leptin provided deep insights into the regulation of central nervous system energy balance circuits, as well as an effective therapy for an extremely rare form of obesity, its therapeutic impact beyond that has been surprisingly limited." (PMID 30357355, 2019). "Our group has shown that the activation of iNOS by leptin in AT is necessary for the synthesis and secretion of the profibrogenic and proinflammatory tenascin C, an important glycoprotein involved in the etiopathology of obesity via AT inflammation and fibrosis." (PMID 31500090, 2019).